BCL2 (BCL2 apoptosis regulator)
Diseases named in the same sentence as BCL2 in open-access papers (continued):
Sharing a sentence is not in itself a finding about the gene and the disease.
pancreatic cancer (continued). "Our data support the view that miR-34 may be involved in pancreatic cancer stem cell self-renewal, potentially via the direct modulation of downstream targets Bcl-2 and Notch, implying that miR-34 may play an important role in pancreatic cancer stem cell self-renewal and/or cell fate determination." (PMID 19714243, 2009). "However, it remains uncertain as to whether AKT or NF-κB is involved in the mechanism of BCL-2 transcriptional activation in pancreatic cancer." (PMID 12865934, 2003). "The antiapoptotic effect of AKT activation in pancreatic cancer cells may involve transcriptional induction of a profile of BCL-2 proteins that confer resistance to apoptosis; alteration of this balance allows sensitisation to the apoptotic effect of chemotherapy." (PMID 12865934, 2003). "The current study examines the hypothesis that a survival signal from AKT activation is mediated by NF-κB and subsequent transcriptional regulation of BCL-2 gene family members; furthermore, inhibition of this pathway sensitises pancreatic cancer cells to the apoptotic effect of gemcitabine." (PMID 12865934, 2003). "In pancreatic cancer, COL11A1 modulates apoptotic inhibition and chemoresistance by activating the Akt/CREB/BCL-2/BAX signaling pathway." (PMID 40927672, 2025). "In pancreatic cancer, curcumin analogs have been demonstrated to act as PI3K inhibitors, reduce Bcl2 levels, and elevate procaspase-3 protein levels." (PMID 41339896, 2025). "It effectuates tumor cell apoptosis through the activation of the JNK/c-Jun and JNK/SAPK pathways, leading to reduced Bcl-2 levels and elevated Bax, as well as activated Caspase-3 and PARP in oral cancer (YD10B and Ca9-22) and pancreatic cancer cells." (PMID 40490812, 2025). "For example, β-sitosterol dramatically suppressed G0/G1 phase arrest, Bcl-2 expression, and NF-kB and Akt/GSK-3β activity, while increasing Bax expression in pancreatic cancer to prevent cancer progression." (PMID 40487864, 2025). "Previous studies have shown that silencing PROK1 exerts its anti-pancreatic cancer effects by inhibiting the PI3K/AKT/mTOR pathway, leading to increased levels of Bax and Cleaved Caspase 3, and decreased levels of PCNA and Bcl-2 in pancreatic cancer cells." (PMID 40961099, 2025). "Immunohistochemical results of Ki67, Bcl2, Vimentin, and LC3A/B exhibit the same trend, demonstrating that CaCO3@CM-OA also exerted a good anti-pancreatic cancer effect in vivo." (PMID 41377584, 2025). "BAG4 has been found to be overexpressed in pancreatic cancer and positively correlated with ANXA7, HSP70 and BCL-2." (PMID 40870378, 2025). "Luteolin, as a natural small molecule inhibitor of BCL-2, shows pro-apoptotic activity in SW1990 pancreatic cancer cells promotes BAX release, and induces cancer cell death by directly binding to BCL-2." (PMID 39840099, 2024). "More importantly, the survival of a transgenic mouse model of pancreatic cancer KPC treated with a combination of plumbagin and xanthohumol was significantly increased, and the effect on BCL2 levels has been confirmed." (PMID 38397018, 2024). "Upregulation of bcl-2, Bcl-xL, and Mcl-1 and downregulation of Bax and NOXA lead to gemcitabine resistance in pancreatic cancer." (PMID 38884675, 2024).
pancreatic cancer (continued). "Upon reintroduction of miR-34 into pancreatic cancer cells through either using miR-34 mimics to transfect or through lentiviral MiR-34-MIF infection, a decrease of Bcl-2 and Notch1/2 occurred." (PMID 38725047, 2024). "Depletion of senescent CAFs, either genetically or using the Bcl-2 inhibitor ABT-199 (venetoclax), increased the proportion of activated CD8+ T cells in mouse pancreatic carcinomas, whereas induction of CAF senescence had the opposite effect." (PMID 39039076, 2024). "Specifically, Bcl-2, Claspin, METTL3 and YTHDF3 were identified as the potential targets of celastrol treatment in pancreatic cancer cells." (PMID 38110764, 2023). "We demonstrated that celastrol treatment reduced total RNA m6A modification in pancreatic cancer cells by down-regulating METTL3 expression, especially decreased Claspin and Bcl-2 mRNA m6A modification, which induced the Claspin and Bcl-2 mRNA decay." (PMID 38110764, 2023). "Furthermore, miR-34a plays a significant role in making pancreatic cancer cells more responsive to chemotherapy and radiotherapy, ultimately leading to the suppression of cancer growth and the induction of cell apoptosis by inhibiting the expression of Bcl-2 and Notch signaling pathways." (PMID 38139352, 2023). "Furthermore, we noted that YTHDF3 overexpression partially rescued celastrol-induced downregulation of Claspin and Bcl-2, and abrogated the celastrol-mediated suppression of cell proliferation and cell cycle progression, and the induction of apoptosis in celastrol-treated in pancreatic cancer cells." (PMID 38110764, 2023). "Mechanistically, activation of caspase-3, suppression of anti-apoptotic BCL2 and BCL-XL expression, and increased PARP cleavage were detected in pancreatic cancer cells upon treatment with low doses of 2d." (PMID 37514107, 2023). "KL-6 treatment also resulted in the downregulation of Bcl-2 and MCL1, two genes that suppress apoptosis, suggesting that KL-6 triggers apoptosis in pancreatic cancer cells." (PMID 37927794, 2023). "More evidence is needed to assess the priorities between BCL-2 and BCL-XL inhibition for pancreatic cancer treatment." (PMID 37894324, 2023). "Further study revealed that celastrol treatment downregulated Claspin and Bcl-2 in an m6A-YTHDF3-mediated manner, which providing a novel mechanism for the therapeutic application of celastrol in pancreatic cancer." (PMID 38110764, 2023). "Taken together, our data clearly indicated that celastrol treatment downregulated Claspin and Bcl-2, at least in part, in an m6A-YTHDF3-mediated manner in pancreatic cancer cells." (PMID 38110764, 2023). "Our study highlighted a novel mechanism underlying celastrol-induced cellular proliferation inhibition and apoptosis in pancreatic cancer cells via m6A-YTHDF3-mediated downregulation of Claspin and Bcl-2." (PMID 38110764, 2023). "In glioblastoma, non-small cell lung cancer, and pancreatic cancer, ATF5 regulates the protein expression of deubiquitinase USP9X, which, in turn, stabilizes B cell lymphoma 2 (BCL-2) and myeloid leukemia 1 (MCL1)." (PMID 35864539, 2022). "Another study also indicated that luteolin induced apoptosis of pancreatic cancer cells in vivo by inhibiting KRAS-GSK-3β-NF-κB signaling pathways, accompanied by cytochrome C release, caspase 3 activation, and Bcl-2/Bax ratio decreases." (PMID 35408691, 2022). "Meanwhile, the levels of cleaved-PARP and Caspase-3 proteins in pancreatic cancer cells with overexpression of DUSP6 were significantly increased, while the BCL2 protein was decreased, suggesting that DUSP6 promotes the apoptosis of pancreatic cells." (PMID 36017891, 2022). "In pancreatic cancer, knockdown of GSK-3β leads to a decrease in Bcl-2 and VEGF levels, thereby inhibiting tumor growth and angiogenesis." (PMID 34719320, 2022).
pancreatic cancer (continued). "Studies have confirmed that the pro-apoptotic gene BAX is significantly downregulated in pancreatic cancer cells with GEM acquired resistance and that the ratio of BAX/BCL-2 can predict GEM sensitivity." (PMID 35680938, 2022). "LDL-C can promote the proliferation of pancreatic cancer cells by activating the STAT3 pathway and upregulating the levels of oncogenes such as Bcl-2, Bcl-xL, survivin controlled by this transcription factor in pancreatic cancer cells." (PMID 35251975, 2022). "Matrine in nude BALB/c mice inhibits tumor development of pancreatic cancer cells in a dose-related mode by inducing apoptosis through stimulation of CASP3, CASP8 and CASP9, reducing the BCL2:BAX ratio and upregulating FAS." (PMID 36497321, 2022). "In pancreatic cancer PCa cells in high concentration, this compound can upregulate pro-apoptotic genes such as BAX, whereas it downregulates anti-apoptotic genes such as BCL2." (PMID 36497321, 2022). "Our studies demonstrate the growth inhibitory action of steviol in human pancreatic cancer (HPAF-II and AsPC1) cells via inducing apoptosis, as indicated by PARP cleavage and upregulation in Bax and inhibition in Bcl-2 and Bcl-xl." (PMID 34944630, 2021). "To better understand the mechanism of PART1 on pancreatic cancer cell apoptosis, we measured the effect of PART1 knockdown on Bcl-2 and Bax protein expression." (PMID 33865422, 2021). "To re-confirm our IHC/IF results with pancreatic tissues from KPC mice, the saline or GNE-495-treated pancreatic tumor extracts were blotted with antibodies for MAP4K4, MLK3, PCNA, α-SMA, cleaved caspase 3, c-PARP, Bax, and Bcl2." (PMID 34511598, 2021). "The western blot results showed activation of p-GSK 3β and up-regulation of N-CA, Bcl-2, and Ki67 in response to HMGB1 stimulation, while E-CA expression was down-regulated in pancreatic cancer cells in response to HMGB1 stimulation." (PMID 34805222, 2021). "These mechanistic changes induced increased expression of the pro-apoptotic Bax protein and decreased expression of the anti-apoptotic Bcl-2 protein, which resulted in enhanced apoptosis in PANC-1, CFPAC-1, MiAPaCa-2 and Capan-2 pancreatic cancer cell lines." (PMID 32717779, 2020). "In addition, irisin has been shown to suppress pancreatic cancer cell growth and proliferation, and to enhance doxorubicin-induced pancreatic cancer cell apoptosis through the upregulation of caspase-3 expression and the reduction of anti-apoptotic B-cell lymphoma 2 (Bcl-2) and Bcl-xL expression." (PMID 33195249, 2020). "NF-κB-regulated anti-apoptotic Bcl-2, Bcl-xL, c-IAPl, and surviving in human ovarian carcinoma cells, Cox-2 and VEGF in human pancreatic cancer cells." (PMID 31354475, 2019). "In this study, DHA was shown to reduce viability of pancreatic cancer cells (PANC-1) by inducing DNA fragmentation, activating caspase-3, and increasing the ratio of Bax/Bcl-2." (PMID 30400136, 2018). "qRT-PCR analysis showed that mRNA expression level of Bcl-2 decreased and Bax, Caspase-3, and Caspase-9 increased in a dose-dependent manner after SW1990 pancreatic cancer cells were incubated with 18F-FDG for 24h." (PMID 28881676, 2017). "This miRNA was found not only to inhibit the proliferation of pancreatic cancer cells, but also to promote cells apoptosis in vitro through the suppression of CCKBR and Bcl-2 expression." (PMID 27187371, 2016). "Hu Q. and colleagues demonstrated that some of the molecular targets that are regulated by miR-34a in pancreatic cancer are E2F3 (E2F transcription factor 3), Bcl-2, c-MYC and cyclin D1." (PMID 27187371, 2016). "The upregulation of ERK1/2-dependent Bcl-2 and downregulation of ERK1/2-dependent Bax can protect human pancreatic cancer cells from gemcitabine-induced apoptosis." (PMID 25880226, 2015). "A siRNA approach for silencing BCL-2 expression has demonstrated BCL-2 down-regulation and tumour regression in the PANC-1 pancreatic cancer xenograft model." (PMID 26077929, 2015).
pancreatic cancer (continued). "In terms of human pancreatic cancer, ABT-737 and obatoclax, which inhibits Bcl-2, Bcl-xL, and Mcl-1, were shown to enhance the TRAIL sensitivity of pancreatic cancer cell lines." (PMID 26506422, 2015). "We initially compared the in vitro antitumor effect of two orally bioavailable Bcl-2 inhibitors, ABT-263 and ABT-199, and found that ABT-263 was able to sensitize human pancreatic cancer cells to TRAIL." (PMID 26506422, 2015). "In pancreatic cancer, inhibition of either phosphatidylinositol-3 kinase or AKT led to a decreased protein level of the antiapoptotic gene BCL-2 and an increased protein level of the proapoptotic gene BAX." (PMID 26229955, 2015). "In pancreatic cancer, downstream targets of AKT sensitized cells to the apoptotic effect of chemotherapy by NF-κB/Bcl-2 signalling pathway." (PMID 26229955, 2015). "We investigated methylation levels at selected CpG sites in the CpG rich regions at the promoter regions of p16, RARbeta, TNFRSF10C, APC, ACIN1, DAPK1, 3OST2, BCL2 and CD44 in the blood of 30 pancreatic tumor patients and in the blood of 49 matching controls." (PMID 22629410, 2012). "For SGS we chose the human pancreatic cancer cell line MiaPaCa-2, which expresses XIAP, Bcl-2 and Survivin and AsPC-1 cells, which express XIAP and Survivin." (PMID 20646298, 2010). "Our data showed that the expression of Bcl-2, Bcl-xL, Notch-1, and survivin proteins was significantly induced in response to CXCL12 treatment of pancreatic cancer cells." (PMID 21045835, 2010). "Previously, we showed that inhibition of GSK-3 resulted in apoptosis induction through decreased expression of NF-κB target genes Bcl-2 and XIAP in CLL and pancreatic cancer cells." (PMID 19920820, 2009). "The results showed that GAPDH, Bcl-2 and IGFBP6 were amplified from the positive contrasting template, which confirmed the presence of GAPDH, Bcl-2 and IGFBP6 genes in the total chromatin fraction of pancreatic cancer cells." (PMID 19736394, 2009). "Similarly, protein expression of Bcl-2 decreased and Bax increased when CASC19 was silenced in pancreatic cancer cell line MIAPaCa-2." (PMID 41023804, 2025). "This selectivity of venetoclax for Bcl-2, without broadly disrupting calcium signaling in healthy pancreatic tissue, is crucial for its potential clinical application in pancreatic cancer." (PMID 40841912, 2025). "Collectively, our findings indicated that Claspin, Bcl-2, METTL3, and YTHDF3 might be the potential targets of celastrol treatment in pancreatic cancer cells." (PMID 38110764, 2023). "In summary, the findings present here provided in vitro and in vivo evidences demonstrating that downregulation of Bcl-2, Claspin, METTL3 and YTHDF3 was involved in celastrol-induced cellular proliferation inhibition, cell cycle arrest and apoptosis in pancreatic cancer cells." (PMID 38110764, 2023). "Notably, we found that celastrol treatment mediated the reduction of m6A levels of Claspin and Bcl-2 mRNA by downregulating METTL3, leading to the degradation of Claspin and Bcl-2 mRNA in pancreatic cancer cells." (PMID 38110764, 2023). "Collectively, our data clearly indicated that Claspin and Bcl-2 might be the targets of YTHDF3, and celastrol treatment downregulated Claspin and Bcl-2 in an m6A-YTHDF3-mediated manner in pancreatic cancer cells." (PMID 38110764, 2023). "Furthermore, we revealed that celastrol treatment downregulated Claspin and Bcl-2, at least in part, in an m6A-YTHDF3-mediated manner in pancreatic cancer cells." (PMID 38110764, 2023). "Additionally, the restoration of miR-34 in human pancreatic cancer BxPC3 and MiaPaCa2 cells induces apoptosis and enhances sensitivity to GEM by inhibiting the expression of Notch1, Notch2, and Bcl-2." (PMID 38139352, 2023). "In addition to Bax/Bcl2, Ole (200 μM) promoted apoptosis in in vitro MIA PaCa-2 pancreatic cancer cells via the dimerization of c-Jun and c-Fos into AP1." (PMID 36013319, 2022).
pancreatic cancer (continued). "COL11A1/Akt disturbed the BCL-2/BAX balance, inhibiting cytochrome c (Cyt-C) release and binding of Apaf-1/procaspase-9/Cyt-C, which suppressed the apoptotic program and induced GEM resistance in pancreatic cancer cells." (PMID 33531986, 2021). "Furthermore, an analog of TQ induced apoptosis by downregulating Bcl-2, Bcl-xL, survivin, XIAP, COX-2 combined with Gemcitabine and oxaliplatin in Gemcitabine resistant pancreatic cancer MiaPaCa-2 cells." (PMID 33916916, 2021). "After treatment with 100ng/ml exogenous HMGB1, the western blot results showed the activation of p-GSK 3β and the up-regulation of N-CA, Bcl-2, and Ki67 in response to HMGB1 stimulation, while E-CA expression was down-regulated in pancreatic cancer cells in response to HMGB1 stimulation." (PMID 34805222, 2021). "In pancreatic cancer xenograft models, it was found that Nimbolide induced apoptosis is related to the increase in the expression of Bax, C-Caspase-3 and lytic PARP; and the decrease in the expression of the anti-apoptotic protein Bcl-2." (PMID 35222011, 2021). "Additionally, our data showed that COL11A1/Akt/CREB altered the balance between BCL-2 and BAX and mediated their mitochondrial translocation in pancreatic cancer cells." (PMID 33531986, 2021). "In our study, we treated MDA-MB-231 and 4T1 cells with DXL and we observed that the activations of survivin and Bcl-2 were increased and the level of p-IκBα was a little upregulated, which indicated that DXL induced the chemo-resistance of pancreatic cancer cells." (PMID 32625089, 2020). "Additionally, a study on pancreatic cancer and CDC26 showed that CCDC26 was responsible for the growth and apoptosis of pancreatic cancer cells, partly by regulating PCNA and Bcl2 expression." (PMID 31619233, 2019). "Other groups reported that the IL-6/JAK2 signaling pathway inhibits autophagy, via p-STAT3, which activates Bcl-2 to regulate the expression of Beclin 1 and VPS34, while in pancreatic cancer, IL-6 induces mitochondrial localization of p-STAT3 at Ser727, upregulating autophagy flux." (PMID 32565533, 2019). "In the present study, changes of expressions of anti-apoptotic proteins such as bcl-2, mcl-1, and transporter proteins were examined in pancreatic cancer cells co-cultured with TAMs, but no significant changes were observed (data not shown)." (PMID 30537992, 2018). "The BAX gene, a member of the Bcl-2 apoptotic protein family with pro-apoptotic activity, has previously been shown to be a direct target of EGR1, which subsequently led to apoptosis induction in pancreatic cancer cells." (PMID 29719592, 2018). "In this study, we found that infection of VV-ING4 reduced the ratio of Bcl-2/Bax and induced the activation of Caspase 8/9/3 and PARP in SW1990 human pancreatic cancer cells, suggesting that Caspase-dependent apoptosis and the Bcl-2 family is participated in VV-ING4-induced cytotoxicity." (PMID 29137298, 2017). "Taken collectively, the data suggest that HIF1-α mediates activation of BNIP3 under hypoxic conditions that results in the induction of the mitochondrial pathway of apoptosis in pancreatic cancer cells, via the modulation of the expression of the proteins Bax, AIF and Bcl-2." (PMID 28968982, 2017). "For example, My-AKT and BCL-2 expression promotes the ability of cancerous cells to multiply without undergoing apoptosis, but is not known to alter the mechanical phenotype of pancreatic cancer cells directly." (PMID 27265611, 2016). "In human pancreatic cancer cells, inhibition of ERK1/2 activities caused downregulation of antiapoptotic proteins BCL-2, MCL-1, and BCL-Xl without affecting the proapoptotic proteins BAX and BAK." (PMID 27656657, 2016). "We therefore tested the hypothesis that pancreatic cancer cells are resistant to gemcitabine and this resistance is due to activation of ERK1/2 and subsequent upregulation of Bcl-2 and downregulation of Bax." (PMID 25880226, 2015).